WNT5A (Wnt family member 5A)
Diseases named in the same sentence as WNT5A in open-access papers (continued):
Sharing a sentence is not in itself a finding about the gene and the disease.
morbid obesity (1 paper, 2022). An excess of body weight, normally defined as an individual with a body mass index greater than 35 or a body weight greater than one hundred percent of ideal body weight. "Similarly, in our previous study, we evaluated SFRP5 serum levels and hepatic SFRP5, WNT5A and c-Jun N-terminal kinase (JNK), an intermediate of the noncanonical WNT5A pathway, mRNA expression in patients with morbid obesity (MO) and NAFLD." (PMID 36077270, 2022).
non‐alcoholic steatohepatitis (1 paper, 2021). "Therefore, treatment of anti‐inflammatory cytokine IL‐10 in 3T3‐L1 pre‐adipocytes or celecoxib in diabetic rat could suppress the adipogenesis and reverse the non‐alcoholic steatohepatitis (NASH) via targeting this non‐canonical Wnt5a pathway." (PMID 34042263, 2021).
omphalocele (1 paper, 2025). Omphalocele is an embryopathy classified in the group of abdominal celosomias and is characterized by a large hernia of the abdominal wall, centered on the umbilical cord, in which the protruding viscera are protected by a sac. "Malrotation can be caused by alteration in left-right asymmetry pathways and indeed Hand1Hand2/Hand2 Visium and RNAscope expression analysis reveals changes in Wnt5a and Pitx2 expression, which are known causes of omphalocele." (PMID 40960281, 2025). "Malrotation of the gut is an established mechanism causing omphalocele and gut rotation is in part mediated by left-right signaling involving the transcription factor Pitx2 via Wnt5a signaling." (PMID 40960281, 2025). "Wnt5a knockout mice present with gut malrotation defects, suggesting the observed decrease in Wnt5a expression contributes to the observed omphalocele phenotype." (PMID 40960281, 2025).
oral cancer (1 paper, 2020). "The findings of this study indicate that Egr inhibitors and Wnt5a antibodies are potential therapies for treatment of OSF and oral cancer." (PMID 33167868, 2020).
Osteoblastoma (1 paper, 2020). A rare benign bone-forming neoplasm usually arising from the spine. "One conventional osteoblastoma displayed a novel mechanism of FOS upregulation; bringing the entire FOS gene under the control of the WNT5A enhancer that is itself activated by FOS." (PMID 32542935, 2020).
papilloma (1 paper, 2015). A benign epithelial neoplasm that projects above the surrounding epithelial surface and consists of villous or arborescent outgrowths of fibrovascular stroma. "We validated by qRT-PCR the upregulation of EMT drivers, such as Zeb1, Zeb2, Twist and Prrx1, and EMT mediators, such as Wnt5a, Vcan, Ncadh and Mmp2 both in Nanog-papillomas and in Nanog-SCCs." (PMID 25988972, 2015).
parathyroid tumors (1 paper, 2021). "Therefore, receptor and post-receptor downregulation of the CASR signaling may be associated with downregulated WNT5A, in line with the previously reported WNT5A downregulation in parathyroid tumors." (PMID 33670622, 2021).
peripheral nerve injury (1 paper, 2024). Injury to a peripheral nerve. "In peripheral nerve injury induced neuropathic pain model, a satisfactory anti-allodynia effect with about 6 weeks pain-relief duration were achieved through targeting microglia strategy, which decreased microglia activation and inflammation by Wnt5a, a non-canonical Wnt pathway." (PMID 38519978, 2024).
Peutz-Jeghers syndrome (1 paper, 2015). An autosomal dominant disorder caused by pathogenic variants in the STK11 gene, characterized by hamartomatous polyps in the gastrointestinal tract, mucocutaneous pigmentation and increased risk of GI and extra-GI malignancies. "In support of a role for the non-canonical pathway in LKB1 loss Wnt5a expression has recently been shown to be elevated in polyp formation in Lkb1+/− mice and Peutz-Jeghers syndrome." (PMID 26056085, 2015).
polycystic ovarian syndrome (1 paper, 2016). "In the ovary, Wnt5A acts as a pro-inflammatory factor in the ovarian granulosa cells of women with polycystic ovarian syndrome." (PMID 28536612, 2016).
pulmonary tuberculosis (1 paper, 2016). A bacterial infection that affects the lungs and is caused by Mycobacterium tuberculosis. "This review focuses on the regulation of Wnt5a, Wnt3a, and the recently identified Wnt6 and their functional role in bacterial infections with a primary focus on pulmonary tuberculosis, a leading infectious cause of morbidity and mortality worldwide." (PMID 28082976, 2016).
respiratory distress syndrome (1 paper, 2008). "The lung phenotype of the GMAP210 mutant mouse is similar to several mouse models of infantile respiratory distress syndrome caused by defects in signaling between cells of the developing lungs such as the Wnt5a and the nitric oxide synthase (eNOS) mutant." (PMID 19112494, 2008).
rickets (1 paper, 2022). Bone softening and weakening usually caused by deficiency or impaired metabolism of vitamin D. Deficiency of calcium, magnesium, or phosphorus may also cause rickets. "Taken together, our findings provide a potential novel and mechanistic explanation of Rickets symptoms have uncovered an essential connection between Notch function and control of Wnt5a expression, with a key master regulatory function in skeletal development." (PMID 35694720, 2022).
Right ventricular hypertrophy (1 paper, 2020). In this case the right ventricle is more muscular than normal, causing a characteristic boot-shaped (coeur-en-sabot) appearance as seen on anterior- posterior chest x-rays. "Taken together, in the present study, our results confirmed that MSC‐EXO could significantly suppress the vascular remodelling and right ventricular hypertrophy induced by MCT, which through regulation of Wnt5a and/or BMPR2 signalling pathway and then inhibition of EndMT process." (PMID 33090702, 2020).
Salmonella Infections (1 paper, 2024). Infections with bacteria of the genus SALMONELLA. "The already documented IgG1-dependent protection against Salmonella infection and the low level of IgG1-expressing B cells in the Wnt5A heterozygous mice as compared to wild-type, furthermore, strengthened the possibility of increased damage from Salmonella infection in the Wnt5A heterozygous mice." (PMID 39140737, 2024).
Shock (1 paper, 2015). The state in which profound and widespread reduction of effective tissue perfusion leads first to reversible, and then if prolonged, to irreversible cellular injury. "The levels of Wnt5a, Fzd5, total CaMKII, and phosphorylated CaMKII in the lung from rats with endotoxic shock were significantly increased when compared with the Control group." (PMID 26218875, 2015).
Splenomegaly (1 paper, 2022). Abnormal increased size of the spleen. "The average size of spleen and its weight per unit weight of body was also considerably more in the Wnt5A heterozygous mice following infection with either AG83 or BHU575, as compared to the control, confirming increased infection induced splenomegaly therein." (PMID 35197983, 2022).
ulcer (1 paper, 2015). "Our results demonstrated that in mice, the basal expression level of Wnt5a in intestinal fibroblasts is much higher than hematopoietic cells or epithelial cells, and that DSS administration induces Wnt5a expression in fibroblasts located in ulcer lesions." (PMID 26030277, 2015). "In addition, Wnt5a was still expressed in the mesenchyme of ulcer lesions in Wnt5aMxΔ/Δ mice but not in Wnt5aCAGΔ/Δ mice." (PMID 26030277, 2015).
Umbilical hernia (1 paper, 2021). Protrusion of abdominal contents through a defect in the abdominal wall musculature around the umbilicus. "Vertebral segmentation defects and ribs fusion occur in the recessive form linked to ROR2 mutations (MIM# 268310) whereas umbilical hernia and supernumerary teeth are more common in the autosomal dominant forms due to WNT5A (MIM# 180700), DVL1 (MIM# 616331), DVL3 (MIM# 616894) mutations." (PMID 35096710, 2021).
Usher syndrome (1 paper, 2025). A syndromic diseae characterized by the association of sensorineural deafness (usually congenital) with retinitis pigmentosa and progressive vision loss. "IGHV1-69D and GAD1 demonstrated statistically significant upregulation in Usher syndrome samples compared to controls (p < 0.05), while WNT5A and DIP2C exhibited a significant downregulation (p < 0.05)." (PMID 40723835, 2025). "According to our meta-analysis of transcriptomic data, IGHV1-69D and GAD1 are significantly upregulated, whereas WNT5A and DIP2C are significantly downregulated in Usher syndrome." (PMID 40723835, 2025). "Among these, WNT5A and CBS were significantly downregulated in Usher syndrome, whereas the remaining eight genes showed upregulation." (PMID 40723835, 2025).
ventricular septal defect (1 paper, 2012). The presence of a defect (opening) in the septum that separates the two ventricles of the heart. "Analysis of Wnt5a−/− embryos (n = 5) revealed ventricular septal defects (VSD) and abnormal positioning of the great arteries (aorta and pulmonary trunk), which were side-by-side." (PMID 22438823, 2012).
visceral leishmaniasis (1 paper, 2022). A severe form of leishmaniasis characterized by irregular bouts of fever, substantial weight loss, swelling of the spleen and liver, and anemia (which may be serious). "We demonstrated that depletion of Wnt5A in Wnt5A heterozygous mice increases susceptibility to experimental visceral leishmaniasis following infection with either AG83 or BHU575." (PMID 35197983, 2022). "Taken together our results indicate that while depletion of Wnt5A promotes susceptibility to visceral leishmaniasis, revamping Wnt5A signaling in the host is able to curb L. donovani infection irrespective of antimony sensitivity or resistance and mitigate the progression of disease." (PMID 35197983, 2022). "Altogether, these results suggest that the altered status of splenic macrophages and T cells, and the IFN-γ linked proinflammatory cytokine bias associated with Wnt5A signaling support parasite clearance and help restrict disease progression in experimental visceral leishmaniasis." (PMID 35197983, 2022). "Accordingly, in a mouse model of experimental visceral leishmaniasis we explored the utility of host Wnt5A in restraining L. donovani infection, using both antimony sensitive and antimony resistant L. donovani strains." (PMID 35197983, 2022). "In this study we evaluated the potential of Wnt5A signaling in restraining disease progression in a mouse model of experimental visceral leishmaniasis using both antimony sensitive (AG83) and antimony resistant (BHU575) strains of L. donovani." (PMID 35197983, 2022). "Administration of recombinant Wnt5A (rWnt5A) prior to L. donovani infection, on the other hand, renders resistance to the development of experimental visceral leishmaniasis." (PMID 35197983, 2022). "In view of the fact that Wnt5A signaling antagonizes L. donovani infection in macrophages we wanted to examine if Wnt5A signaling regulates the progression of experimental visceral leishmaniasis." (PMID 35197983, 2022). "In order to evaluate the influence of Wnt5A signaling on experimental visceral leishmaniasis in mice, we examined if the administration of recombinant Wnt5A (rWnt5A) is efficacious in preventing L. donovani infection and the progression of disease." (PMID 35197983, 2022). "However, in view of several other reports related to the uncertain status of IL-4 in the context of visceral leishmaniasis, the significance of the Wnt5A-IL-4 connection in our study is unclear at present." (PMID 35197983, 2022).
Wilms tumor (1 paper, 2023). An embryonal neoplasm characterized by the presence of epithelial, mesenchymal, and blastema components. "Nonetheless, together with our finding of specific upregulation of WNT5A in tumors harboring the SIX1/2-Q177R mutation, this observation indicates that WNT5A may be a direct regulatory target of SIX1/SIX1-Q177R in Wilms tumor." (PMID 37815464, 2023). "An earlier analysis of WNT5A expression in FHWT Wilms tumors has demonstrated a positive correlation between low WNT5A expression (compared to expression in hFK control) and blastemal predominant histology." (PMID 37815464, 2023). "Considering the relevance of WNT5A in other cancers, our findings suggest that further investigations of WNT5A in Wilms tumor, and its potential as a therapeutic target, are warranted." (PMID 37815464, 2023). "SIX1 ChIP-seq datasets from Wilms tumors revealed shared binding sites for SIX1/SIX1-Q177R within a promoter of WNT5A and at putative distal cis-regulatory elements (CREs)." (PMID 37815464, 2023). "Though it has been extensively studied in cancer and may both activate or inhibit cancer progression dependent on tissue context, investigations of WNT5A in Wilms tumor are scarce." (PMID 37815464, 2023). "In doing so and when compared to other blastemal tumors, we identified upregulated expression of the gene encoding the non-canonical WNT ligand WNT5A in both chemotherapy-naïve and chemotherapy-treated blastemal Wilms tumors harboring the SIX1-Q177R mutation." (PMID 37815464, 2023). "To address the possibility of WNT5A regulation by SIX1, we turned to available SIX1 ChIP-seq data generated from wild-type SIX1 and SIX1-Q177R mutant Wilms tumors." (PMID 37815464, 2023). "While we do not directly compare the magnitude of WNT5A expression in Wilms tumors to that in hFK, the results of our DGE analysis appear to generally agree with the findings by Tamimi and colleagues, except in the case of SIX1/2-Q177R tumors." (PMID 37815464, 2023). "In addition to a site bound only by SIX1-Q177R, Wilms tumor ChIP-seq peaks containing SIX1/SIX1-Q177R motifs bound by both SIX1 and SIX1-Q177R, were identified at proximal and distal regions near the WNT5A locus." (PMID 37815464, 2023). "Utilizing multiple Wilms tumor transcriptomic datasets, we identified upregulation of the gene encoding non-canonical WNT ligand WNT5A in addition to other WNT pathway effectors in SIX1/2-Q177R mutant tumors." (PMID 37815464, 2023).
tumor (519 papers, 1998 to 2026). "Mechanistically, WNT5A, secreted by tumor-associated macrophages (TAMs) under hypoxia, activates ROR1-mediated Wingless-type MMTV integration site family (WNT) signaling in GSCs, promoting GDEC formation." (PMID 41562250, 2026). "The WTN5A (Wnt Family Member 5A) gene, which encodes a signaling glycoprotein and its mutation, has been associated with various tumor types." (PMID 40868849, 2025). "On the other hand, genes encoding tumor-enriched matrisome proteins were predominantly expressed in desmoplastic fibroblasts and WNT5A+ inflammatory fibroblasts." (PMID 40032993, 2025). "By integrating scRNA-seq datasets from CRC tissues, we found that the tumor-enriched proteins were predominantly associated with desmoplastic fibroblasts and WNT5A+ inflammatory fibroblasts." (PMID 40032993, 2025). "WNT ligands (e.g., WNT2, WNT5A) from tumor cells and cancer-associated fibroblasts (CAFs) in the TME activate the Wnt pathway through the proliferation of CSCs and resurrection of dormant CSCs, causing treatment resistance and cancer recurrence." (PMID 38952556, 2024). "We found that WNT5a expression is negatively associated with tumor stage, LNM, as well as FIGO stages." (PMID 37335710, 2023). "Wnt5a overexpression has been implicated in the aggressiveness of diverse tumor types and has been shown to promote cell invasion and metastasis." (PMID 36672361, 2023). "Bioinformatic analysis revealed that in ACC tumor tissues, overexpressed Wnt5A was associated with poorer prognostic survival, including progression-free interval (PFI), disease-specific survival (DSS), and overall survival (OS)." (PMID 38269250, 2023). "We also identified two fibroblast populations differentiated by WNT5A expression level, which we annotated as WNT5A-intermediate and WNT5A-high tumor-associated fibroblasts." (PMID 36008377, 2022). "Through the B cell proliferation in WNT5A-deficient mice, WNT5A was found to inhibit B cell proliferation through WNT/calcium to act as a tumor suppressor." (PMID 35957916, 2022). "In contrast to WNT5A expression in tumor cells, which was associated with a longer OS, stWNT5A had no influence on overall or CSS." (PMID 33639039, 2021). "High CXCL12 expression in CAFs significantly correlated with the histological grade (P=0.012) and TNM stage (P=0.014), while Wnt5a expression was associated significantly with primary tumor category (P=0.016)." (PMID 33854601, 2021). "In a study, it has been reported that hypermethylation of the Wnt5a promoter has been significantly associated with enhancing tumor stage, which is mediated by increasing DNMT1 activity in CRC tissue." (PMID 34603445, 2021). "Wnt5a has been implicated in tumor progression, raising concerns about its potential use as a GI radioprotective agent in cancer patients." (PMID 34900719, 2021). "Wnt5a pro-tumour activity was found to be associated with the overexpression of the C-C motif chemokine ligand 2 (CCL2) in Wnt5a-treated macrophages." (PMID 33080952, 2020). "The Wnt5a suppressive properties detected in tumours connoted by β-catenin hyper-activation have been linked to the shift towards the stimulation of the β-catenin independent signalling pathway." (PMID 33080952, 2020). "On the other hand, the tumor suppressor role of Wnt5a is commonly associated with low expression of this ligand." (PMID 32195251, 2020). "This intracellular pathway is also initiated by Wnt ligand proteins, most commonly WNT5A, which has been implicated as a tumor suppressor in multiple cancer types." (PMID 32560059, 2020). "It has also been reported that loss of Wnt5a is associated with a higher histological tumour grade, increased risk of recurrence, and a shorter recurrence-free survival in invasive BC." (PMID 33080952, 2020). "The up-regulation of WNT5A in HRS cells within a proportion of tumours has been noted and a recent study implicated WNT5A in cell migration in HL." (PMID 30546079, 2019).